CLDN18 (claudin 18)
Diseases named in the same sentence as CLDN18 in open-access papers (continued):
Sharing a sentence is not in itself a finding about the gene and the disease.
adenocarcinoma (17 papers, 2013 to 2026). A common cancer characterized by the presence of malignant glandular cells. "Particularly in the serrated adenocarcinoma subtype, CLDN18 expression has been closely linked to an increase in lymph node metastases and more advanced overall staging." (PMID 40936686, 2025). "Eight of 14 (57%) CD-associated adenocarcinomas were positive for CLDN18, and 5 (36%) lesions showed ≥ 40% extent expression and 2 (14%) of them showed ≥ 75% extent expression." (PMID 39164422, 2025). "Cadherin17 and Claudin 18 expression was identified in 93% and 57% CD-associated adenocarcinomas respectively." (PMID 39164422, 2025). "Expression of CLDN18 within the serrated adenocarcinoma subtype was associated with a greater degree of metastatic lymph nodes and advanced overall stage." (PMID 38540693, 2024). "Seven of 13 (54%) CDH17-positive CD-associated adenocarcinomas were positive for CLDN18." (PMID 39164422, 2025). "Accordingly, zolbetuximab-based chemotherapy was selected for this case of CLDN18.2-positive adenocarcinoma with a gastric phenotype arising from ectopic gastric epithelium." (PMID 41256328, 2025). "The expert working group reviewed the literature on CLDN18 IHC in G/GEJ adenocarcinoma and developed consensus recommendations on the testing algorithm, as well as pre-analytical, analytical, and post-analytical considerations." (PMID 39727695, 2024). "The expert working group recommends reflex testing for HER2, MMR and/or MSI, CLDN18, and PD-L1 in all patients with G/GEJ adenocarcinoma at the time of diagnosis." (PMID 39727695, 2024). "CLDN18 IHC is a new biomarker test that is not currently in clinical use for G/GEJ adenocarcinoma or any other cancer disease site." (PMID 39727695, 2024). "Claudin-18 was detected in high levels in gastric epithelial cells at the apical and lateral side borders in non-IM but not in IM or differentiated adenocarcinoma cells." (PMID 24073219, 2013). "In normal tissues, the CLDN18.2 epitope within the tissue adhesion complex is completely inaccessible; however, on malignant transformation, cell adhesion is disrupted, and the CLDN18.2 epitope is exposed on the gastric and GEJ (G/GEJ) adenocarcinoma cell surface, making it a promising target." (PMID 38136288, 2023). "Our results showed that regardless of adenocarcinoma or dysplasia, CDH17 expression was retained in most CD-SBNs and CLDN18 expression was seen in 56% of CD-SBNs with a strong association with the expression of gastric mucins." (PMID 39164422, 2025). "Thus, ZOL-FO for CLDN18.2-positive, HER2-negative advanced G/GEJ adenocarcinoma is not cost-effective in China." (PMID 37719841, 2023).
infection (9 papers, 2012 to 2025). The state of being infected such as from the introduction of a foreign agent such as serum, vaccine, antigenic substance or organism. "Among tight junction-associated genes, CLDN11 was downregulated in both infections at 24 hpi, whereas CLDN16 and CLDN18 were specifically downregulated following Delta infection." (PMID 41200555, 2025). "Claudin18 (CLDN18), a TJ protein, is significantly downregulated in all infection groups compared to the control group." (PMID 40979361, 2025). "Results showed that MUC5AC, FGB, and CLDN18 were highly expressed only in the control group and L3 infection group, while CCL19 exhibited higher expression levels in the infection groups." (PMID 40979361, 2025). "These are involved in smooth-muscle function (FGFR1, GATA5 and STIM1), tissue organization (ADAMTS10), alveolar and epithelial function (ABCA3 and CLDN18), and inflammation and immune response to infection (CFH, CYTL1, HMCN1, LRBA and STIM1)." (PMID 36914875, 2023). "Moreover, in this intranasal infection model, increased mRNA levels of Cdh1 (E-cadherin), Tjp1 (ZO-1), Cldn4 (claudin 4), Cldn5 (claudin 5), and Cldn18 (claudin 18) were observed after IFN-β treatment." (PMID 36559113, 2022). "Importantly, we found significant resistance to oxaliplatin and 5-fluorouracil after introduction of CLDN18-ARHGAP26 in vitro with different infection systems, providing the possible explanation of poor drug response of patients with such fusion." (PMID 29961079, 2018).
gastrointestinal tumors (5 papers, 2023 to 2025). "The expression and clinical significance of CLDN18 in GI tumours." (PMID 36969060, 2023).
cardiovascular diseases (1 paper, 2025). "Since junctional alterations are well-documented features of cardiovascular diseases, the dysregulation of CLDN18 could represent a novel contributor to the atherosclerotic process." (PMID 41226477, 2025).
CLDN18 also shares sentences with these, for which no sentence is quoted: cholangiocarcinoma (2 papers); glioma (2); prostate carcinoma (2); sarcoma (2); signet ring cell carcinoma (2); allergies (1); bacteremia (1); bile duct adenocarcinoma (1); biliary tract cancer (1); breast carcinoma (1); bronchopulmonary dysplasia (1); carcinoma of the uterine cervix (1); cervical cancer (1); chronic gastritis (1); colitis (1); congenital heart disease (1); COVID-19 (1); digestive system cancer (1); end-stage renal disease (1); endocervical adenocarcinoma (1); esophageal squamous cell carcinoma (1); gallbladder cancer (1); gallbladder tumors (1); Gastric Metaplasia (1); genitourinary cancers (1); Hearing impairment (1); hematological malignancies (1); hyperplastic (1); hyperplastic polyp (1); hypertriglyceridemia (1).
A further 25 diseases each share a sentence with CLDN18 in 1 paper.